TRBJ2-6 (T cell receptor beta joining 2-6)
Description:
J region of the variable domain of T cell receptor (TR) beta chain that participates in the antigen recognition. Alpha-beta T cell receptors are antigen specific receptors which are essential to the immune response and are present on the cell surface of T lymphocytes. Recognize peptide-major histocompatibility (MH) (pMH) complexes that are displayed by antigen presenting cells (APC), a prerequisite for efficient T cell adaptive immunity against pathogens. Binding of alpha-beta TR to pMH complex initiates TR-CD3 clustering on the cell surface and intracellular activation of LCK that phosphorylates the ITAM motifs of CD3G, CD3D, CD3E and CD247 enabling the recruitment of ZAP70. In turn ZAP70 phosphorylates LAT, which recruits numerous signaling molecules to form the LAT signalosome. The LAT signalosome propagates signal branching to three major signaling pathways, the calcium, the mitogen-activated protein kinase (MAPK) kinase and the nuclear factor NF-kappa-B (NF-kB) pathways, leading to the mobilization of transcription factors that are critical for gene expression and essential for T cell growth and differentiation. The T cell repertoire is generated in the thymus, by V-(D)-J rearrangement. This repertoire is then shaped by intrathymic selection events to generate a peripheral T cell pool of self-MH restricted, non-autoaggressive T cells. Post-thymic interaction of alpha-beta TR with the pMH complexes shapes TR structural and functional avidity.
Synonyms: TRBJ26; TCRBJ2S6
Gene: T-cell receptor joining (J) gene on chromosome 7 (142,797,239 to 142,797,291, forward strand). Ensembl gene ENSG00000211770.
Subcellular location: Cell membrane